MMP2 (matrix metallopeptidase 2)
Diseases named in the same sentence as MMP2 in open-access papers (continued):
Sharing a sentence is not in itself a finding about the gene and the disease.
tumor (continued). "Through the Comparative Toxicogenomics Database—CTD database—among the 15 EMT genes described, four genes (MMP2, MAP1B, SNAI2, and WNT5A) were related to neoplasms and brain disorders, named neuronal EMT-related genes." (PMID 36553576, 2022). "IHC was used to detect the expression of NF-κB, MMP9, MMP2, and TIMP-2, which are the four key targets for tumor migration and invasion." (PMID 35770085, 2022). "The MMPs, MMP-2, and MMP-9 are the most related to tumor metastasis and invasion, because they have gelatinases activity and can degrade the extracellular matrix." (PMID 35711540, 2022). "The relative expressions of AKT1, MMP2, and MMP9 genes were higher in tumour tissues than in non‐neoplastic liver tissues." (PMID 35811356, 2022). "In summary, we found that ST3GAL6-AS1 positively regulates ST3GAL6 in LUAD cells, while the depletion of ST3GAL6-AS1 activates the EGFR signaling pathway, upregulates the expressions of MMP2 and 9, and promotes the invasion of LUAD tumor cells." (PMID 36092699, 2022). "Previous studies provided evidence that MMP2 and MMP9 triggered cell migration and invasion, and they were two major MMPs involved in tumor angiogenesis, increasing the bioavailability of VEGF." (PMID 35494062, 2022). "First, SIS3 inhibited the promotion of the expression of MMP2, MMP13 and VEGF induced by GluOC in tumor cells." (PMID 35413833, 2022). "MMP-2 and VEGF have been well-characterized by promoting cancer cell invasion and metastasis via degrading the extracellular matrix and increasing tumor angiogenesis." (PMID 34976177, 2022). "The protein expression of RAB26, Ki67, PCNA as well as MMP2 and MMP7 in xenograft tumor tissues from each group was also determined by western blot assay." (PMID 35291909, 2022). "The MMP2-overexpressing tumor microenvironment deprotected PEG, exposing it to TATp, facilitating tumor penetration and subsequent efficient destruction of tumor cells." (PMID 36104946, 2022). "Exosomal miRNAs (miR-100-5p and miR-21-5p) derived from prostate CSCs increase MMP2/9 expression and enhance the MMP-mediated migration of tumour cells, contributing to local invasion and premetastatic niche formation." (PMID 35158891, 2022). "MMP-2 (Gelatinase A) and MMP-9 (Gelatinase B) are known to significantly contribute to tumor invasion and progression through their proteolytic actions." (PMID 36230480, 2022). "Obviously, the addition of JM2 in the cell culture medium significantly suppressed the gene expressions of MMP2 and MMP9 in both types of tumor cells." (PMID 35332127, 2022). "The analysis revealed that the relative expressions of AKT1, MMP2, and MMP9 genes were increased in HCC tumour tissues (n = 373) compared with the normal samples (n = 50)." (PMID 35811356, 2022). "VEGF activated the downstream targets of PI3K pathways in the tumor microenvironment by binding to VEGFR2, including membrane type-1 (MT1-MMP) and MMP2, ultimately leading to the formation of the VM structure." (PMID 35379271, 2022). "Their data demonstrated a tumor-suppressing role of PRSS3 in HCC via multiple pathways, including downregulation of matrix metallopeptidase 2 (MMP2) and deactivating MEK1-ERK1/2 signaling." (PMID 36618965, 2022). "Among MMPs, MMP-2 and MMP-9 are receiving renewed interest as validated druggable targets for halting different tumor progression events." (PMID 34638665, 2021). "Within the TME, TAMs have been shown to migrate deep into tumor hypoxic regions where they can support tumor cell migration and invasion via ECM remodeling by the upregulation of MMP-2, -7, and -9, and stimulate angiogenesis through enhanced VEGFA production." (PMID 34884995, 2021). "Crocin significantly inhibits tumour growth, and it also downregulates MMP2 and MMP9, which are involved in extracellular matrix degradation of tumour cells." (PMID 34256821, 2021). "MMP2, MMP7, and MMP9 are members of the MMP family and are mainly involved in tumour invasion and metastasis." (PMID 33995637, 2021).
tumor (continued). "It has been reported that high levels of matrix metalloproteinases, such as MMP-1, MMP-2, MMP-9, and MMP-14, produced by tumor cells participate in VM37." (PMID 33850110, 2021). "Altogether, Mmp2-OE tumors appear to be selectively depleted of stem-like CD8+ T cells and NK cells, both important for tumor control when activated." (PMID 34032639, 2021). "CXCR2, CXCR3, and CXCR4, up‐regulate EMT‐TFs (snail and ZEB1), promote MMP‐2 expression, and accelerate EMT of cancer cells, thereby promoting tumor metastasis." (PMID 34977870, 2021). "The ELTSL is expected to accumulate selectively in the tumour through the enhanced permeability and retention effect, and then subsequently strip the PEG corona through MMP-2-mediated cleavage of peptide spacer for deeper penetration inside the tumour." (PMID 34946732, 2021). "Increased expression of MMP-2 and MMP-9 was reported to induce tumor angiogenesis, inflammation, and cancer metastasis." (PMID 33926142, 2021). "GBM cells produce different ECM components such as hyaluronic acid (HA), matrix metalloproteinase-2 (MMP2), matrix metalloproteinase-9 (MMP9), integrins, tenascin-C, and fibronectin to degrade and remodel the ECM for tumor invasion." (PMID 33670551, 2021). "Matrix metalloproteinase-2 (MMP-2), metalloproteinase-9 (MMP-9), and vascular endothelial growth factor (VEGF) are key factors in tumor invasion and metastasis during angiogenesis." (PMID 34988028, 2021). "Results demonstrated a significant reduction in tumor size and the highest levels of IFN-γ and IL-17 and the lowest levels of IL-4 FoxP3, HIF-1α, VEGF, MMP-2, and MMP-9 in the IT+IP+TEX-treated group." (PMID 34194604, 2021). "Western blot result uncovered that Ki67, PCNA, MMP-2, and MMP-9 were notably repressed upon ADAMTS9-AS1 overexpression (p < 0.05), indicating that the tumor proliferation was decreased." (PMID 34900984, 2021). "Given the critical function of MMP-2 and MMP-9 in tumor cell migration and invasion, we investigated the effect of sh-LINC00488 on the protein expression levels of MMP-2 and MMP-9." (PMID 33600548, 2021). "Among these, MMP-2 and MMP-9 are of particular relevance since they are usually overexpressed in tumor cells and are capable of degrading type IV collagen of basement membrane, the first barrier for cancer invasion." (PMID 34202184, 2021). "Like MMP2, MMP9 also degrades ECM components of the basement membrane to help facilitate tumor invasion while TIMP1 regulates MMP9 activity." (PMID 33995488, 2021). "In fact, previous studies have demonstrated that miR-29b-3p directly modulated the expression of MMP-2 and MMP-9 in the tumor microenvironment and thus indirectly regulate epithelial plasticity." (PMID 33740985, 2021). "A positive correlation was found between the MMP‐2 and IGF‐1R expression in OSCC tumours (p < 0.0001)." (PMID 34528373, 2021). "As MMP-2 and MMP-9 are believed to play a critical role in tumor invasiveness, we determined the expression of these proteinases using Western blotting." (PMID 34934771, 2021). "It has been shown that some members of the family of MMPs promote tumor growth, angiogenesis, epithelial–mesenchymal transition (EMT), and premetastatic niche formation in cancer patients, as is the case with MMP-1, MMP-2, MMP-3, and MMP-9." (PMID 34445715, 2021). "After log-transformation, the following biomarkers displayed a normal distribution and statistically significant differences in tumor vs. control (in alphabetical order): APRIL, BAFF, CA19-9, pERK, IL-1β, IL-1RA, IFN-β, IL-26, MMP-2, and TWEAK." (PMID 33846436, 2021). "Several metalloproteinases such as MMP2, MMP3, MMP9 and MT1-MMP have been shown to be upregulated in lymph nodes or lung tissues distant from the primary tumor by tumor-derived exosomes." (PMID 33809973, 2021). "Matrix metalloproteinase 2 (MMP2), a type of matrix metalloproteinase (MMP), plays a major role in tumour invasion and is well‐characterized in BC prognosis." (PMID 34142438, 2021).
tumor (continued). "In the previous publication, it is shown that sub-curative radiation increases tumor cell proliferation, migration, and invasion in a rat model of primary human GBM primarily by the increased expression level of MMP2, HIF-1α, and SDF-1α." (PMID 33544755, 2021). "Here, we showed that the enzymatic activities of MMP2 and MMP9 were very low in normal tissues, while higher levels of both pro- and active forms were detected in the paired tumor samples of 24 patients." (PMID 34830271, 2021). "For example, MMP2 and MMP9 expression levels were significantly higher in tumour tissues than in normal tissue samples in BC." (PMID 34142438, 2021). "Overproduction of MMP2//9 induces the degradation of the major components of ECM and BM, allowing the escape of tumor cells and promoting subsequent metastasis." (PMID 33568081, 2021). "Evaluates the expression of angiogenic factors secreted by tumor cells, such as VEGF, bFGF, etc.Evaluates the expression of matrix metalloproteinases secreted by tumor cells, such as MMP-2, MMP-9, etc." (PMID 34746014, 2021). "Previous studies showed that the expression levels of MMP2, MMP7 and MMP9 is positively correlated with the plasticity of tumor cells, such as invasion depth, metastasis distance, and vascular permeability." (PMID 34696818, 2021). "A study on MMP-2 knockout mice was able to show that MMP-2 plays a key role in angiogenesis and tumor progression." (PMID 34041592, 2021). "Tumor promotor FAM129A has recently been reported to activate FAK signaling pathway and upregulate MMP2 and MMP9 in tumor tissues." (PMID 34513838, 2021). "The protein concentrations of MMP-1, MMP-2, MMP-3, and MMP-9 also have been seen to be greater in OSCC tumor tissue in contrast to control tissue." (PMID 33892690, 2021). "The linker is a substrate of MMP-2, designed to be cleaved by MMP-2 so that the ELP system can eventually release a complex of the payload (doxorubicin) and a CPP (CPP-Dox) in tumor tissues." (PMID 33498762, 2021). "Based on matrix metalloproteinase 2 and 9 (MMP-2/9), frequently overexpressed proteases in tumor environment, they constructed a masked CPP–DOX conjugate." (PMID 33805680, 2021). "Among these MMPs, MMP2 and MMP9 can selectively degrade type IV collagen, promoting tumor cells migrating through the basement membrane." (PMID 34820358, 2021). "PEG was modified on the surface of the vesicle through the MMP-responsive linker—GALGLPG (A short peptide), and when the vesicles reached tumor site, the GALGLPG peptide was cleaved by MMP-2 and then removed PEG to increase the endocytosis of the vesicles." (PMID 34796163, 2021). "Given their importance in tissue remodelling and organ development, abnormal MMP expression (especially MMP‐2, MMP‐9 and MMP‐14) is seen in a host of diseases, from autoimmune disorders to cancers, impacting tumour and immune‐cell microenvironments." (PMID 33675132, 2021). "Through the interaction between the coated gelatin layer and the MMP-2 in the ECM, large-sized gold NPs become smaller, which enables deeper tumor infiltration." (PMID 33968752, 2021). "Ginsenoside Rg3 can decrease the expression of MMP-2, MMP-9 and VEGF in B16 cell tumor mouse model and in vitro B16 cell model." (PMID 34746014, 2021). "Downregulation of IL-8 expression levels in stressed mice resulted in lower levels of MMP-2 and MMP-9 in the tumor microenvironment and abolished the effect of stress on tumor metastasis." (PMID 35011682, 2021). "Among MMP types, MMP2 and MMP9 promote the invasion and metastasis of tumor cells by degrading type IV collagen, a main component of the ECM." (PMID 33747258, 2021). "In vitro, the ciRS‐7/miR‐876‐5p/MAGE‐A family axis was also corroborated to facilitate tumour growth and metastasis by increasing proliferation markers (Ki67 and PCNA) and metastatic markers (matrix metalloproteinase 2 [MMP2] and MMP9)." (PMID 34510785, 2021).
tumor (continued). "Activation of β-adrenergic signaling through NE has been shown to promote epithelial to mesenchymal transition (EMT) through upregulation of MMP2/9 and VEGF thereby enhancing the invasive and metastatic properties of tumor cells." (PMID 34790909, 2021). "MMP-2 and MMP-9 are zinc-dependent ECM degrading enzymes involved in the metastatic activity of tumor cells." (PMID 34400947, 2021). "In view of the regulation of E-cad, MMP-9, MMP-2, and vimentin, the results showed that TPL/NPs effectively suppressed tumor metastatic effects in vivo." (PMID 34162396, 2021). "Western blot result uncovered that Ki67, MMP-9, MMP-2, PCNA and other tumor markers were prominently activated after the downregulation of ADAMTS9-AS1, indicating increased tumor proliferative activity." (PMID 34900984, 2021). "As we found the reduced mRNA levels of matrix metalloproteinase (MMP) 2 and MMP9 in tumor tissues from LNCaP xenografts injected with GV1001, we further assessed both mRNA and protein expressions of MMP2 and MMP9 in LNCaP cells exposed to vehicle or GV1001." (PMID 34743733, 2021). "The expression levels of MMP2, MMP9, Bax, Bcl-2, and caspase-3 in the tumor organizations were detected with Western blot." (PMID 33391431, 2021). "Our studies illustrated that miR-1258 functioned as a tumor suppressor in GBM by directly targeting E2F1, subsequently inhibiting PCNA and MMP2 transcriptions, which contributed to new potential targets for GBM therapy and other E2F1-driven cancers." (PMID 34079762, 2021). "It is well known that local invasion is the first requirement for distant metastasis, while a key event in tumor invasion is degradation of the surrounding ECM, which involves activation of MMP-2 and MMP-9 6,8." (PMID 34149918, 2021). "The protein expression level of MMP-2 and MMP-9 was significantly enhanced with the increase of the tumor clinical stages and the metastasis of lymph nodes (N staging)." (PMID 31882379, 2021). "Whereas some of the MMPs (e.g., MMP-7) are expressed by the cancer cells, other MMPs (MMP-2 and MMP-9) are synthesized by the tumor stromal cells, including myofibroblasts, fibroblasts, endothelial cells, and inflammatory cells." (PMID 34684168, 2021). "In addition, high TSP4 expression levels were associated with advanced tumour grades and poor survival rates in patients with BC In vitro studies have further demonstrated that the migratory potential of BC cells is significantly enhanced in response to TSP4 treatment, caused by MMP2 expression." (PMID 34142438, 2021). "It has been shown that LPS promotes tumour invasion through the TLR4‐mediated activation of the NF‐κB pathway, resulting in the up‐regulation of matrix metalloproteinase 2 (MMP2) and the β1‐integrin subunit." (PMID 33336901, 2021). "In cancer, the overproduction or increased activity of MMP2/9 leads to the degradation of ECM and BM, allowing for the invasion of tumor cells to other tissues and tumor cell metastasis to distant organs." (PMID 33568081, 2021). "Through our immunohistochemical results, we could see that markers such as ACTA2, VIM, and MMP2 were mostly differentially expressed in the stromal area, including CAFs and vascular smooth muscle cells, but not in the tumor cells between the different risk score groups." (PMID 33747932, 2021). "Our previous investigations have also demonstrated that serum MMP-2 and TIMP-2 concentrations decrease with tumor stage, while MMP-2 levels are significantly lower in patients with CRC in comparison to those with CA." (PMID 34071492, 2021). "As the main component of the tumor stroma, MAFs can remodel the ECM in metastatic lesions by expressing factors such as fibronectin, TGFβR2, collagen 1, matrix metalloproteinase-2 (MMP2) and other molecules." (PMID 34112258, 2021). "We found that the protein level of MMP2, MMP7, MMP9, MMP12, and MMP14 in the tumor tissue were basically higher than that in the normal tissue." (PMID 34804973, 2021).
tumor (continued). "In this study, a comparison of MMP2 and MT1-MMP expression in 6 stromal cells and 7 tumor cell lines revealed a strong correlation between the levels of protease expression and the capacity of these cells to degrade gelatin." (PMID 33740019, 2021). "Specifically, MMP2 and MMP9 are considered to be critical in tumor metastasis because of their influences on ECM degradation and tissue remodeling." (PMID 33430855, 2021). "As the fibrin cluster, the peptidase cluster contained many differentially overexpressed MMPs, including MMP2, in the LMS4/F2T2↑ tumor but also in FGFR3 tumors." (PMID 33853673, 2021). "MMP-2 and MMP-3 have the ability to degrade collagen II, IV, IX, X, XI, and gelatine, which is known to be critical for tumor invasion and metastasis." (PMID 34078895, 2021). "MAFs facilitate the metastatic tumor cell invasive phenotype in peritoneal metastases, possibly via TGF-β1, HGF and MMP2." (PMID 34112258, 2021). "The western blotting assays of tumor tissue lysates showed that TSN inhibited the PI3K/Akt/mTOR signaling pathway and the expression of MMP-2, cyclin D1, and Bcl-2 proteins." (PMID 34530814, 2021). "Our study also determined the tumor-suppressing function of SNHG1 knockdown at molecular levels, corresponding to reductions in MMP-2, MMP-9, Bcl-2, and N-cadherin and elevations in Bax and E-cadherin." (PMID 34095464, 2021). "Here, we found that curcumin not only inhibited the growth of xenografts in chronically stressed nude mice, but also decreased the expression of matrix metalloproteinase (MMP)‐2/9 and CD147 in tumour tissues." (PMID 34169637, 2021). "Compared with si-ADAMTS9-AS1 + DMSO group, the expression levels of Ki67, PCNA, MMP-2 and MMP-9 in si-ADAMTS9-AS1 + INCB018424 group were prominently constrained, indicating decreased tumor proliferative activity (p < 0.05)." (PMID 34900984, 2021). "Western blot result exhibited that compared with si-NC + DMSO group, the expression levels of Ki67, PCNA, MMP-2 and MMP-9 in si-ADAMTS9-AS1 + DMSO group were markedly boosted, indicating increased tumor proliferative activity." (PMID 34900984, 2021). "It has been reported that MMP-2 and MMP-9 are extracellular proteolytic enzymes that play an important role in tumor invasion." (PMID 33737656, 2021). "There were significant correlations between MMP-2 immunoreactivity in inflammatory cells and the presence of distant metastases, and between TIMP-2 expression in inflammatory cells and tumor size, nodal involvement and distant metastases." (PMID 34071492, 2021). "Due to their capacity to degrade basement membrane components, the gelatinases MMP2 and MMP9 are key molecules for the spreading of tumor and metastatic progression." (PMID 34830271, 2021). "Tien-Hsien Liquid possesses antimetastasis capacity by decreasing MMP-2, MMP-9 and uPA expression and tumor growth and promoting antiangiogenic effects." (PMID 34659548, 2021). "Activated MMP-2 was observed in various tumor tissues, suggestive of pro-MMP-2 activator(s) present in the tumor microenvironment." (PMID 34203581, 2021). "The protein levels of LIMK1, p-cofilin, cofilin, p-CREB, CREB, MMP2, ITGB1, and COL1A1 in mouse tumor tissues were consistent with the metastatic potential of the tumor in mice." (PMID 34079084, 2021). "The mesenchymal components including MMP-2 and MMP-9 can contribute to tumor invasion through breaking down of basement membrane including Coll-IV." (PMID 33937253, 2021). "An experiment in which T739 mice were injected subcutaneously with LA795 mouse lung adenocarcinoma cells showed that after RPS treatment, mRNA levels of MMP-2 and -9 were reduced and TIMP-2 was upregulated in tumor tissues." (PMID 34639167, 2021). "Knocking down LINC02535 also significantly inhibited the EMT, a key contributor to tumor invasion and metastasis, by inducing the expression of SNAIL, MMP2, and CDH2 (N-cadherin)." (PMID 33869203, 2021).